SPATA31H1 (SPATA31 subfamily H member 1)
Synonyms: C2orf16; DKFZp434G118
Gene: Protein-coding gene on chromosome 2 (27,537,386 to 27,582,722, forward strand). Ensembl gene ENSG00000221843.
Subcellular location (Human Protein Atlas): Nuclear bodies; Cytosol; Nucleoplasm
Genetic constraint (gnomAD): Loss-of-function variants: 1 observed, 1.78 expected, observed/expected ratio (o/e) 0.56, 90% interval 0.18 to 1.79. That is too few expected variants to judge how well the gene tolerates losing a copy. Missense variants: 2,178 observed, 2,510.4 expected, observed/expected ratio (o/e) 0.87, 90% interval 0.84 to 0.9. Synonymous variants: 807 observed, 887.26 expected, observed/expected ratio (o/e) 0.91, 90% interval 0.86 to 0.96.
Homologues: Orthologues: chimpanzee SPATA31H1 (97% identical), macaque SPATA31H1 (90% identical), mouse Spata31h1 (39% identical), mouse Spata31h-ps1 (28% identical), dog C17H2orf16 (20% identical), rat AABR07063276.1 (10% identical).
Diseases named in the same sentence as SPATA31H1 in open-access papers:
SPATA31H1 is named in the same sentence as 11 diseases in open-access papers, as found by Europe PMC text mining. Sharing a sentence is not in itself a finding about the gene and the disease.
SPATA31H1 shares sentences with these, for which no sentence is quoted: hypertriglyceridemia (2 papers); type 2 diabetes (2); autism spectrum disorder (1); dyslipidemia (1); endometriosis (1); gastric cancer (1); glucose metabolism disorder (1); gout (1); Hypertension (1); neurodegenerative disease (1); neuroendocrine disorder (1).